SMAD3 (SMAD family member 3)
Diseases named in the same sentence as SMAD3 in open-access papers (continued):
Sharing a sentence is not in itself a finding about the gene and the disease.
renal fibrosis (continued). "Elevated TGFβ1 and downstream Smad3 and Smad2 in the kidney activate profibrotic genes and mediate renal fibrosis." (PMID 31531112, 2019). "We previously showed Smad2 protects against renal fibrosis by limiting Smad3 signaling, but details on its role in acute phase are unclear." (PMID 31754396, 2019). "Smad3 promotes renal fibrosis by directly binding to the promoter region of ECM molecules to trigger their production." (PMID 31557800, 2019). "A number of studies demonstrated that targeting Smad3 can ameliorate the development and progression of tissue fibrosis in vivo, including experimental models of renal fibrosis, pulmonary fibrosis, and liver fibrosis." (PMID 30287731, 2018). "This is consistent with previous studies that have shown that Smad3 and Smad2 can counteract each other especially in renal fibrosis and inflammation." (PMID 29700311, 2018). "On the other hand, TGF-β1-induced extracellular matrix expression was attenuated by elevated levels of SIRT1, supporting the idea of protective role of SIRT1 in the development of renal fibrosis due to its action on TGF-β/Smad3 signaling." (PMID 30298020, 2018). "HDAC6 contributes to renal fibrosis through regulation of epigenetic histone modification and Smad3-dependent fibrotic genes." (PMID 30134806, 2018). "Of interest is that conditional deletion of SMAD2 enhanced renal fibrosis, because SMAD2 deficiency induced excess phosphorylation of SMAD3, resulting in the SMAD3 binding to a collagen promotor and auto-induction of TGF-β." (PMID 30150520, 2018). "TGF-β1 is an important mediator during the progression of renal fibrosis through the activation of several signaling pathways, including the Smad3 pathway." (PMID 30232404, 2018). "We found that celastrol inhibited the progression of renal fibrosis by upregulating CB2R expression through inhibiting Smad3 signaling pathway activation." (PMID 29789558, 2018). "In this pathway, TGFβ1 mainly transduces its fibrotic signal through activation of TGFβreceptor 1 (TGFβR1) followed by phosphorylation and nuclear translocation of Smad3, thus driving the progress of renal fibrosis." (PMID 30524310, 2018). "Studies show that up-regulation of Sirt1 deacetylase activity attenuates TGF beta-induced renal fibrosis and hepatocyte apoptosis through inhibiting Smad3 signal." (PMID 28030827, 2017). "And then, phosphorylated Smad2 and Smad3 recruit Smad4 forming the Smad complex, being a transactivator, which translocates into the nucleus to regulate the renal fibrosis related target gene transcription." (PMID 28912732, 2017). "The results showed that siRNA Klotho-treated mice displayed slight increase of renal fibrosis, phosphorylated Smad3 and reduced BMP-7." (PMID 28387374, 2017). "In conclusion, MA-35 reduces the inflammatory response by inhibiting TNF-α/IKK signaling and prevents renal fibrosis by inhibiting TGF-β1/Smad3 signaling." (PMID 28507324, 2017). "As TGF-β1 signaling is pivotal for the induction and maintenance of many forms of renal fibrosis, we examined primary signaling events by immunoblotting for phospho-Smad3." (PMID 26914452, 2016). "The in vivo experiments showed that FXR agonist protected against renal fibrosis and downregulated Smad3 expression in UUO mice." (PMID 27853248, 2016). "In this study, we showed that FXR ligand suppresses renal fibrosis and downregulates the expressionin of Smad3 and FN in UUO mice model." (PMID 27853248, 2016). "This had a functional impact since mice reconstituted with Smad3−/− bone marrow showed a substantial reduction in renal fibrosis on the basis of collagen I deposition in the UUO kidney along with reduced mRNA levels for α-SMA and collagen I." (PMID 26684242, 2016). "Among the several TGF-β pathways, Smad3 signaling is considered as a major intracellular pathway, regulating the transcription of target genes involved in renal fibrosis." (PMID 27607429, 2016).
renal fibrosis (continued). "The therapeutic effect of TSF on diabetic kidney injury was associated with the inhibition of NF-κB-driven inflammation and TGF-β/Smad3-mediated renal fibrosis." (PMID 26807792, 2016). "The indices of renal fibrosis, the phosphorylation of Smad3, and the expression of alpha-smooth muscle actin (α-SMA), fibronectin, collagen III (Col III), E-cadherin, TGF-β, and Smad7 in response to DXR were all similarly modified by DAL." (PMID 28100935, 2016). "In this study, we found that FXR inhibited renal fibrosis by downregulating Smad3 at transcriptional level." (PMID 27853248, 2016). "Despite having very high (90%) structural similarity, Smad2 and Smad3 differ in functionality and they play opposing roles in renal fibrosis." (PMID 27610006, 2016). "A novel and significant finding in the present study was that CRP mediated renal fibrosis via the CD32b-Smad3-mTOR signaling pathway." (PMID 27221338, 2016). "For example, Smad3 can promote renal fibrosis and chronic liver disease.Otherwise, the increased Smad3 mRNA expression has been reported in CCl4-induced acute liver injury mice." (PMID 27224286, 2016). "Renal fibrosis is a hallmark of chronic kidney disease including diabetic nephropathy and is mediated by TGF-β/Smad3 signaling." (PMID 26807792, 2016). "The functional importance for the CD32b-Smad3-mTOR pathway in renal fibrosis was further demonstrated by the ability of rapamycin to inactivate the mTOR signaling, thereby inhibiting CRP and high glucose-induced CTGF and collagen I expression." (PMID 27221338, 2016). "In the context of renal fibrosis, Smad3 are strongly activated in both experimental and human kidney diseases." (PMID 28100935, 2016). "CRP alone was able to enhance Smad3-mTOR interaction and induce mTOR/S6K activation and renal fibrosis." (PMID 27221338, 2016). "As the consequence of intact Smad7, activation of both TGF-β/Smad3 signaling and NF-κB signaling in the diabetic kidney was inhibited, thereby resulting in attenuation of renal fibrosis and inflammation." (PMID 26807792, 2016). "Consistent with our previous observation of the protective actions of miR-29 in liver fibrosis, miR-29 also acts as a potent fibrosis-inhibitory regulator that alleviates TGF-β1/Smad3-mediated renal fibrosis and pulmonary fibrosis." (PMID 26938532, 2016). "The mechanism whereby CRP promoted renal fibrosis through the CD32b-Smad3-mTOR mechanism was identified in vivo and in vitro." (PMID 27221338, 2016). "TGFβ1 is a central cytokine in the regulation of renal fibrosis in various models, which initiates fibrosis via the activation of the Smad3 signaling pathway." (PMID 27732564, 2016). "We have recently reported that miR-29b, a negative regulator for the Smad3 and type I collagen is a key regulator in renal fibrosis and pulmonary fibrosis." (PMID 25356754, 2015). "SIS3, a specific inhibitor of Smad3 phosphorylation, can attenuate renal fibrosis in diabetic nephropathy." (PMID 25852569, 2015). "Although Smad2 and Smad3 share more than 90% similarity in their amino acid sequences, their functional roles in renal fibrosis are distinct." (PMID 25852569, 2015). "TGF-β1 acts by stimulating Smad3 to positively regulate miR-21 and miR-192, but negatively regulate the miR-29 or miR-200 families, to mediate renal fibrosis." (PMID 29861424, 2015). "TGF-β is a significant growth factor in PANC that promotes tumor growth and progression, and TGF-β/Smad3 signaling promotes renal fibrosis by inhibiting miR-29." (PMID 25605017, 2015). "In the present study, we report here that inhibition of Smad3 with naringenin (NG) and upregulation of Smad7 with asiatic acid (AA) produced an additive effect on inhibition of renal fibrosis in a mouse model of obstructive nephropathy." (PMID 26474462, 2015). "TGF-β1 promotes the proliferation of mesangial cells, and the TGF-β1/Smad3 signal transduction pathway participates in renal fibrosis." (PMID 26451157, 2015).
renal fibrosis (continued). "Few studies have investigated the roles of Ski and the TGF-β1/Smad3 signaling pathway in renal fibrosis." (PMID 26451157, 2015). "Recent reports have demonstrated that miR-29 acts as a downstream inhibitor and therapeutic miR for TGF-β1/Smad3- mediated renal fibrosis and myogenic differentiation." (PMID 26305546, 2015). "We have previously shown that TGF-β/Smad3 mediates renal fibrosis by upregulating miR-21 but downregulating miR-29b in the UUO and diabetic nephropathy." (PMID 26474462, 2015). "The combination of AA and NG produced an additive effect on inhibition of renal fibrosis by blocking Smad3 while upregulating Smad7." (PMID 26474462, 2015). "Whereas, NG, a flavonoid from grapefruits and citrus fruits, was a Smad3 inhibitor that inhibited renal fibrosis by blocking Smad3 phosphorylation and transcription." (PMID 26474462, 2015). "The functional importance of Smad7 in chronic AAN was demonstrated by the findings that deletion of Smad7 aggravated but restoration of Smad7 locally in the kidneys of Smad7 KO mice prevented AA-induced, TGF-β/Smad3-mediated progressive renal fibrosis." (PMID 25883225, 2015). "Of note, Smad3 promotes renal fibrosis by directly binding to the promoter region of collagens to trigger their production, and inhibiting the ECM degradation via induction of TIMP-1 while reducing MMP-1 activities in fibroblasts." (PMID 25852569, 2015). "In this regard, rebalancing the disturbed Smad3/Smad7 ratio, through downregulating Smad3 and upregulating Smad7 simultaneously, seems to be an effective strategy for treatment of renal fibrosis." (PMID 25852569, 2015). "Recently, miR-433 has been found to be one of the important components of TGF-β/Smad3 driven renal fibrosis." (PMID 25750628, 2015). "Many studies have shown that excessive activation of the TGF-β/Smad3 signaling pathway can promote the progression of renal fibrosis." (PMID 26451157, 2015). "In a recent study of renal fibrosis, it was demonstrated that Smad3 mediated TGF-β1-induced the downregulation of miR-29 by binding to the promoter of miR-29." (PMID 26305546, 2015). "We found that AA, a triterpene from Centella Asiatica, functioned as a Smad7 agonist and suppressed TGF-β/Smad3-mediated renal fibrosis by inducing Smad7." (PMID 26474462, 2015). "It is now clear that Smad3 is a key fibrogenic mediator and is highly activated during renal fibrosis." (PMID 26474462, 2015). "Increasing evidence shows that TGF-β1 is a key mediator in diabetic nephropathy (DN) and induces renal fibrosis positively by Smad3 but negatively by Smad7." (PMID 24646636, 2014). "To elucidate how L-ENG overexpression contributes to increased renal fibrosis, we assessed Smad1 and Smad3 phosphorylation by measuring the abundance of p-Smad1 and p-Smad3 by western blot and immunohistochemistry." (PMID 25313562, 2014). "In this study, we observed increased TGF-β and p-Smad3 in C3a-treated HRGECs and T2DM rats, suggesting that C3a plays an important role in the activation of TGF-β/Smad3 signaling and is a potential inducer of renal fibrosis." (PMID 25422985, 2014). "The exogenous ALR (rhALR) inhibited Smad2 and Smad3 phosphorylation in UUO rats, which served a possible molecular mechanism underlying the antifibrotic capacity of ALR in renal fibrosis." (PMID 24844766, 2014). "The present finding that disrupted Smad7 enhanced Smad3-mediated renal fibrosis added a new evidence for a protective role of Smad7 in ANG II-mediated hypertensive nephropathy." (PMID 23301086, 2013). "We have recently shown that miR-29b is a downstream target of TGF-β/Smad3 signalling and that down-regulation of miR-29b promotes renal fibrosis." (PMID 23301086, 2013). "Smad4 exerts its diverse roles by transcriptionally enhancing Smad3-mediated renal fibrosis while inhibiting NF-κB-driven renal inflammation." (PMID 23301086, 2013).
renal fibrosis (continued). "Endothelial dysfunction and enhanced transforming growth factor-β (TGF-β)/Smad3 signalling are common features of progressive renal fibrosis." (PMID 24391884, 2013). "TGF-betasignaling is associated with almost all forms of kidney disease characterized by renal fibrosis and inflammation, and smad-3 is a critical component of the intracellular pathway that transmits TGF-beta signals from the cell surface into the nucleus." (PMID 22558380, 2012). "In addition, leucine-rich α-2 glycoprotein 1 (LRG1) is elevated in renal fibrosis and promotes renal fibrosis through the TGF-β1/Smad3 signaling pathway." (PMID 40225869, 2025). "Through comprehensive approaches using Smad3-knockout (Smad3-KO) mouse model of UUO and Smad3-KO mouse embryonic fibroblasts (MEFs), we then investigated the regulatory mechanism of TGF-β/Smad3 signaling in GPX4 expression during the development of renal fibrosis in vivo and in vitro." (PMID 41079940, 2025). "Importantly, we also identified that GPX4 is a Smad3 target gene and functions to protect Smad3-mediated renal fibrosis." (PMID 41079940, 2025). "TGF-β/Smad3 signaling is a key pathway leading to the cell death and renal fibrosis." (PMID 41079940, 2025). "This novel finding was functionally confirmed in the UUO mice and mouse embryonic fibroblasts (MEFs) in which deletion of Smad3 protected against UUO and transforming growth factor-β1 (TGF-β1)-induced loss of GPX4, upregulation of TFR1 and 4-HNE, and progressive renal fibrosis in vivo and in vitro." (PMID 41079940, 2025). "Smad2 protects against TGF-beta/Smad3-mediated renal fibrosis." (PMID 40149644, 2025). "In the db/db mouse model, the Smad3 inhibitor SIS3 significantly suppresses TGF-β/Smad3 pathway activation, thereby alleviating renal fibrosis and inflammation while concurrently upregulating Smad7 expression and restoring the balance of the TGF-β/Smad signaling axis." (PMID 41487503, 2025). "Smad3 knockout mice exhibit reduced myofibroblast accumulation in various renal fibrosis models." (PMID 39897045, 2025). "Finally, we explored the potential role of GPX4 in Smad3-driving renal fibrosis by specifically silencing GPX4 in the UUO kidney of Smad3-KO mice and Smad3-KO mouse embryo fibroblasts (MEFs)." (PMID 41079940, 2025). "Research indicates that GLP-1 receptor agonists like liraglutide not only significantly reduce the UACR by activating the renal cAMP-PKA pathway but also directly modulate glomerular hemodynamics and inhibit the TGF-β/Smad3 signaling pathway, thereby attenuating renal fibrosis progression." (PMID 41487503, 2025). "Through the construction of genetically modified mice and in vitro experiments, we demonstrated that deletion of Nrp1 or simultaneous deletion of the genes encoding the TGF-β receptor and Nrp1 delay the progression of renal fibrosis and inhibit Smad3 expression." (PMID 38977708, 2024). "Furthermore, by single-cell RNA-sequencing we find that Nrp1-positive DT cells secrete collagen and communicate with myofibroblasts, exacerbating acute kidney injury (AKI)-induced renal fibrosis by activating Smad3." (PMID 38977708, 2024). "Similarly, a rat model of renal fibrosis induced by a high-salt diet showed a decrease in phosphorylated Smad2 and Smad3 following pirfenidone treatment, indicating that pirfenidone can mitigate fibrosis by altering the Smad signaling pathway." (PMID 39133399, 2024). "The expression of genes that promote renal fibrosis (Smad2, Smad3, Smad4, Shh, Dll1) was downregulated, while the expression of genes that inhibit renal damage (Smurf1, Smurf2, Smad1, Smad5, Smad6, Smad7) was increased in the WT+miPEP31 group (PEP1/2) compared with the WT+ cPEP (SCR1/2) group." (PMID 38992718, 2024). "For example, quercetin alleviates renal fibrosis by inhibiting the TGF-β/Smad3 signaling pathway." (PMID 39687299, 2024).
renal fibrosis (continued). "Mechanically, we uncovered that treatment with SIS3 inhibited T2DN in db/db mice by inhibiting Smad3 while upregulating Smad7, thereby restoring the balance of Smad3/7 signaling and protecting the kidney from the development of progressive renal fibrosis in db/db mice." (PMID 38164169, 2024). "Epigallocatechin gallate inhibits the TGF-β/Smad3 signaling pathway and attenuates renal fibrosis." (PMID 39687299, 2024). "SMAD3 phosphorylation is an important regulatory step in renal fibrosis in CKD." (PMID 39180015, 2024). "Since TGF-β1 mediated the activation of phosphorylation of Smad family, especially Smad3, was a classic pathway for its induction of renal fibrosis, we speculated that this may be related to its up-regulation of TRIM39 expression." (PMID 38195664, 2024). "TGF-β1 regulates microRNAs that mediate renal fibrosis by activating Smad3." (PMID 39471136, 2024). "As a target of SMAD3, Pou4f1 leads to renal fibrosis by promoting MMT." (PMID 38961399, 2024). "It has been reported the important role of Smad3 in renal fibrosis." (PMID 38357745, 2024). "Besides, therapeutic delivery of exosomal miR‐26a can alleviate aldosterone‐induced renal fibrosis by inhibiting CTGF/SMAD3 signalling pathway." (PMID 38898750, 2024). "We thus examined whether treatment with SIS3 inhibits renal fibrosis in T2DN via a Smad3-dependent Erbb4-IR mechanism." (PMID 38164169, 2024). "Pectin alleviates renal fibrosis by inhibiting Smad3 and TGF-β/Smad3 signaling." (PMID 39687299, 2024). "NETs can also drive MMT and, consequently, renal fibrosis via the TGF-β1/Smad3 signalling pathway." (PMID 39445007, 2024). "However, in accordance with a rat study, Smad2 has also been observed to defend against Smad3-dependent collagen accumulation and renal fibrosis both in vivo and in vitro." (PMID 39451219, 2024). "ACY-1215 (a selective HDAC6 inhibitor) could reduce renal fibrosis by inhibiting pro-fibrotic pathways (TGF-β/SMAD3, EGFR), myofibroblast activation, and inflammation." (PMID 38929505, 2024). "Considering the mechanism of TGF-β1 in renal fibrosis, it was found that TGF-β1 causes increased production of ECM like collagen I and fibronectin via Smad3-dependent pathways such as induction of tissue inhibitor of metalloproteinase and trans differentiation of myofibroblast, epithelial cells." (PMID 37559381, 2023). "In addition, TGF-β is a profibrotic molecule that mediates the SMAD-3-dependent canonical pathway of renal fibrosis." (PMID 37374379, 2023). "More recent evidence suggests that CB1 agonism may be influencing renal fibrosis through Smad3 signaling." (PMID 37408253, 2023). "TXNIP overexpression in tubular epithelial cells increases the expression levels of the cellular senescence markers p16INK4a and γH2AX and the profibrotic factors α-SMA, TGF-β1/SMAD3, and collagen I, which ultimately lead to aging-related renal fibrosis and a decline in kidney function." (PMID 37394581, 2023). "Studies have found that the specific deletion of Smad4 from renal tubular epithelial cells attenuates unilateral ureteral obstruction-induced renal fibrosis by suppressing Smad3 responsive promoter activity and reducing the binding of Smad3 to the target genes." (PMID 36835428, 2023).